FABP4 (fatty acid binding protein 4)
Diseases named in the same sentence as FABP4 in open-access papers (continued):
Sharing a sentence is not in itself a finding about the gene and the disease.
diabetes (continued). "FABP4 plays a crucial role in insulin resistance, diabetes mellitus (type 2), gestational diabetes, and other metabolic syndromes." (PMID 36311201, 2022). "For GC patients with diabetes, low FABP4 portends better prognosis than high FABP4 after receipt of rosiglitazone treatment." (PMID 35198079, 2022). "The suppression of FABP4 was reported to relieve the symptom of diabetes and diabetic encephalopathy." (PMID 36670935, 2022). "At 30 weeks of age, diabetes incidence reached 87.5% in FABP4+/+NOD mice but was significantly inhibited to 55.8% in FABP4–/–NOD mice." (PMID 33690220, 2021). "The proportion of patients with diabetic mellitus, systolic BP, total Kt/V, and residual kidney Kt/V of the high FABP4 group were lower than those of the low FABP4 group." (PMID 34789046, 2021). "Pharmacological inhibition of FABP4 at an early age delays onset time and reduces the incidence of diabetes in NOD mice." (PMID 33690220, 2021). "On the other hand, depletion of macrophages only led to a modest reduction in the incidence rate of diabetes (39.4% in GdCl3-treated vs. 49.8% in vehicle-treated group) and a slight improvement in glucose tolerance in FABP4–/–NOD mice." (PMID 33690220, 2021). "Pharmacological inhibition or genetic ablation of FABP4 at an early age is sufficient to reduce autoimmune destruction of β cells and subsequent development of diabetes." (PMID 33690220, 2021). "The onset of diabetes occurred as early as 13 weeks old in FABP4+/+NOD mice, while it was postponed to 21 weeks in FABP4–/–NOD mice." (PMID 33690220, 2021). "The comparison of the proteome and transcriptome confirmed the involvement of fatty acid binding protein 4 (FABP4) in the diet-induced pathogenesis of diabetes in macaques." (PMID 34880765, 2021). "Sitagliptin, a DPP-4 inhibitor, has been reported to decrease FABP4 concentration in drug-naïve and sulfonylurea-treated patients with type 2 diabetes mellitus." (PMID 32539832, 2020). "It has recently been shown that FABP4 concentration is modulated by several therapeutic drugs for diabetes mellitus, dyslipidemia and hypertension." (PMID 33071982, 2020). "Recent studies have also demonstrated modulation of FABP4 concentration by therapeutic drugs for hypertension, dyslipidemia and diabetes mellitus." (PMID 32539832, 2020). "In this study, we sought to investigate whether FABP4 is associated with PAD in patients with type 2 diabetes mellitus (DM)." (PMID 32887447, 2020). "It has been reported that treatment with sitagliptin alone and/or in combination with sulfonylurea decreases serum FABP4 level in patients with type 2 diabetes mellitus." (PMID 32539832, 2020). "In this study, we demonstrated that circulating levels of FABP4 are elevated in PAD patients with diabetes." (PMID 32887447, 2020). "Significant trends were noted in the associations among FABP4 level and heart rate, left ventricular ejection fraction (LVEF), hs-CRP, QTc interval, QRS duration, hypertension, diabetes, HF, and CKD (P for trend < 0.05)." (PMID 31234795, 2019). "Our study confirmed previously established associations with incident diabetes for CD163, FABP4, PAI, and IGFBP-2." (PMID 30670722, 2019). "The results demonstrated that Fabp4 expression was significantly lower in the group with diabetes than that in controls." (PMID 29394254, 2018). "Fabp4 expression level was lower in animals with diabetes, which indicates that the gene is involved in the metabolism of diabetes in adipose tissues in gerbils." (PMID 29394254, 2018). "The present study showed for the first time that canagliflozin, an SGLT2 inhibitor, increased the average serum FABP4 concentration in patients with type 2 diabetes mellitus despite amelioration of glucose metabolism and reduction of adiposity." (PMID 27124282, 2016). "The level of circulating human FABP4 was proposed as an independent prognostic marker for the development of metabolic syndrome, non-alcoholic fatty liver and diabetes." (PMID 26887419, 2016).
diabetes (continued). "In the present study, we investigated the impact of SGLT2 inhibitor therapy on serum FABP4 level in patients with type 2 diabetes mellitus." (PMID 27124282, 2016). "The present study showed that an SGLT2 inhibitor, canagliflozin, increased the average FABP4 level by 10.3% in patients with type 2 diabetes mellitus, though FABP4 level was reduced in 33.3% of the studied patients." (PMID 27124282, 2016). "FABP4 values were significantly higher in obese (2.2±0.86 ng/mL), obese diabetes (2.3±0.87 ng/mL) and CVD subjects (2.7±0.90 ng/mL) compared to control (1.01±0.51 ng/mL) and non-obese diabetes (1.6±0.77 ng/mL) groups." (PMID 23119072, 2012). "This study investigated whether metformin attenuates diabetes-driven renal senescence through the modulation of the fatty acid-binding protein 4 (FABP4)/forkhead box protein O1 (FOXO1) axis and key immunometabolic enzymes." (PMID 41471323, 2025). "Although FABP4, FOXO1, and metformin have previously been implicated in metabolic regulation and inflammation, no study has attempted to establish a connection between these pathways in relation to diabetes-induced kidney aging." (PMID 41471323, 2025). "In individuals with type 2 diabetes, FABP4 concentration was higher compared to those without diabetes, a condition commonly associated with endothelial dysfunction." (PMID 40002815, 2025). "Previous research has indicated that FABP4 may affect cardiomyocytes, contributing to coronary artery disease, heart failure, and diabetes mellitus." (PMID 38731797, 2024). "Fatty acid-binding protein 4 (FABP4) has been associated with cardiovascular disease and diabetes." (PMID 38438929, 2024). "There was also evidence that FABP4 has a significant influence on lipid metabolism by altering the classic lipid profile which is mediated by insulin resistance, particularly in patients with diabetes." (PMID 38731797, 2024). "In a cross-sectional study that evaluated the circulating level of FABP4 in 43 morbidly obese and 38 lean women with no diabetes, there was a significant association between FABP4 and circulating CRP, HOMA-IR, and tumor necrosis factor (TNF)." (PMID 38731797, 2024). "FABP4 inhibitors (FABP4is) are small molecules of therapeutic interest, and ongoing clinical studies indicate that they are promising for treating cancer and other diseases such as metabolic syndrome and diabetes." (PMID 36985701, 2023). "Importantly, targeting hormonal FABP4, either through genetic ablation or monoclonal antibody therapy, has been proven to protect against or reverse diabetes in preclinical models of genetic or diet-induced obesity." (PMID 37172691, 2023). "The aim of our study was to determine the concentrations of adipokines: fetuin A, fatty acid binding protein 4 (FABP4) and retinol binding protein 4 (RBP4) in Cushing’s syndrome and to assess their relation to established cardiovascular and diabetes risk markers." (PMID 36561568, 2022). "In contrast, transplantation of FABP4+/+ BM into FABP4–/–NOD mice significantly increased the incidence of diabetes (71.86% vs. 51.79%) and aggravated insulitis, β cell apoptosis, inflammation, and activation of autoreactive T cells compared with FABP4–/–NOD mice transplanted with FABP4–/– BM." (PMID 33690220, 2021). "All top 30 proteins were associated with diabetes independently of age and sex when examined in linear regression models, and all but one (FABP4) of the associations were also independent of BMI." (PMID 33279861, 2021). "Macrophagic FABP4 contributes to autoimmune destruction of β cells and diabetes in NOD mice." (PMID 33690220, 2021). "However, contradictory results have been published with respect to FABP4 gene expression in patients with metabolic complications and diabetes." (PMID 34609443, 2021).
diabetes (continued). "Consistently, fasting insulin level in BMS309403-treated mice was also higher compared with that in vehicle-treated mice, suggesting that pharmacological inhibition of FABP4 from an early age is sufficient to ameliorate β cell destruction and diabetes in NOD mice." (PMID 33690220, 2021). "However, no previous study has examined the possible association between FABP4 and PAD in patients with diabetes." (PMID 32887447, 2020). "Anagliptin may be able to decrease serum FABP4 concentrations to a greater extent than sitagliptin in patients with type 2 diabetes mellitus and dyslipidemia who are on statin therapy." (PMID 32539832, 2020). "Anagliptin decreases FABP4 concentration independent of change in hemoglobin A1c or LDL-C in patients with type 2 diabetes mellitus at a high risk for cardiovascular events who are on statin therapy." (PMID 32539832, 2020). "When further entering fasting plasma glucose (highly associated with incident diabetes; HR 1.30, 95% CI: 1.25–1.35; p = 9.1 × 10−39) as a covariate (model 3), the following four proteins remained significantly associated with increased risk of diabetes; PAI, Gal-4, CD163 and FABP4." (PMID 30670722, 2019). "When further adjusting for established risk factors (model 2), all 7 proteins remained significantly associated with incident diabetes; 5 proteins (CD163, Gal-4, CTSD, PAI and FABP4) with an increased risk of diabetes and 2 proteins (PON3 and IGFBP-2) with a decreased risk for incident diabetes:." (PMID 30670722, 2019). "Furthermore, it was shown that plasma level of FABP4 can be an indicator of metabolic syndrome, type 2 diabetes mellitus, and increased lipolytic activity of adipose tissue." (PMID 29335416, 2018). "Considering the large number of diabetes patients and the popularity of PPARγ agonists (Rosiglitazone, Pioglitazone) class anti-diabetes drugs, elevated cardiac FABP4 expressions may be quite common among metabolic syndromes patients." (PMID 27294862, 2016). "In conclusion, treatment with canagliflozin paradoxically increases serum FABP4 level in some patients with type 2 diabetes mellitus despite amelioration of glucose metabolism and reduction of adiposity, and this effect is possibly mediated by catecholamine-induced lipolysis in adipocytes." (PMID 27124282, 2016). "In a post-hoc analysis stratified by prevalent diabetes, we demonstrated a higher risk of SCD per SD higher FABP4 in nondiabetics but not in people with diabetes (P for interaction 0.049)." (PMID 24455402, 2013). "If this hypothesis were correct, it would contribute to the mechanisms by which circulating FABP4 contributes to vascular endothelial dysfunction in diabetes." (PMID 22709426, 2012). "Previous studies have shown that FABP4, a member of this family of proteins that are expressed in adipocytes and macrophages, plays pivotal roles in the pathogenesis of various cardiovascular and metabolic diseases, including diabetes mellitus (DM) and hypertension (HT)." (PMID 39062961, 2024). "Therefore, FABP4 might influence insulin resistance and insulin secretion in diabetes mellitus type 2." (PMID 37892985, 2023). "Therefore, the researchers pointed that FABP4 inhibitor therapy may be a beneficial strategy for the treatment of diabetes." (PMID 36060264, 2022). "Our data indicate that protein FABP4, a lipid-binding protein that has a crucial role in DM, was upregulated in the liver of spontaneously occurred diabetes and HFHS-induced diabetes, evidenced by elevation in both hepatic mRNA and protein levels." (PMID 34880765, 2021). "Previous in vivo evidence showed that obese FABP4-deficient mice would not develop insulin resistance or diabetes since they could not express tumor necrosis factor-α (TNF-α) from adipose tissues." (PMID 33287461, 2020).
diabetes (continued). "Furthermore, in the present study, the patients with higher levels of plasma FABP4 also had higher rates of hypertension, diabetes, and HF, thereby raising the possibility that FABP4 directly contributes to cardiac repolarization defects and is associated with QTc prolongation." (PMID 31234795, 2019). "Additionally, a FABP4-specific inhibitor could become a therapeutic drug for diabetes and for arteriosclerosis, as demonstrated in mice." (PMID 28654680, 2017). "Because FABP4 may also increase the risk of type 2 diabetes, it is possible that people with diabetes may be at a higher risk of SCD than nondiabetic individuals." (PMID 24455402, 2013). "Although fatty acid binding protein 4 (FABP4) may increase risk of diabetes and exert negative cardiac inotropy, it is unknown whether plasma concentrations of FABP4 are associated with incidence of sudden cardiac death (SCD)." (PMID 24455402, 2013). "Furthermore, FABP4 has been inversely related to adiponectin and positively related to adiposity, metabolic syndrome, coronary heart disease burden, and diabetes." (PMID 24455402, 2013). "Our findings establish FABP4, CDR2L, and FSTL3 as pivotal regulators at the CRC-diabetes interface, with dual utility as prognostic indicators and predictors of immunotherapy efficacy." (PMID 40595026, 2025). "By integrating multi-omics data from public repositories and applying machine learning-driven feature selection, we identified three core biomarkers—FABP4,CDR2L,and FSTL3 that independently predicted overall survival in CRC patients with diabetes." (PMID 40595026, 2025). "A recent study proved that the depletion of pancreatic TRM cells, either by fatty acid-binding protein 4 (FABP4) or specific antibodies, reduced inflammation and the onset of diabetes in a mice model." (PMID 40277935, 2025). "FABP4 has also been recognized as an important pathological key factor in various systemic diseases, including obesity, diabetes mellitus (DM), hypertension (HT), hyperlipidemia (HL), atherosclerosis, renal disease, metabolic dysfunction, heart events and malignancy." (PMID 38927820, 2024). "In type 1 diabetes mellitus (T1DM), FABP4 plays a regulatory role in glucose and lipid metabolism, particularly in ketogenesis during the insulin-deficient state." (PMID 38731797, 2024). "Consistently, the diabetes incidence in both TRM cell depleted FABP4+/+ NOD mice (52.85%) and FABP4−/− NOD mice receiving IgG (43.73%) at 30 weeks old were significantly attenuated when compared to FABP4+/+ NOD mice receiving IgG (75.83%)." (PMID 38884133, 2024). "Recently, fetuin A, fatty acid binding protein 4 (FABP4) and retinol binding protein 4 (RBP4) were identified as biomarkers of atherosclerotic cardiovascular disease and diabetes." (PMID 36561568, 2022). "In animals, increased FABP4 in pancreatic islets and circulation of NOD mice occurs as early as 4 weeks of age, well before the development of overt diabetes." (PMID 33690220, 2021). "Diabetes incidence was regularly monitored in both FABP4+/+NOD and FABP4–/–NOD mice from 8 weeks old to 30 weeks old." (PMID 33690220, 2021). "We investigated concentrations of FABP4 and FABP5 in patients with type 2 diabetes mellitus who were receiving statin therapy at high risks for cardiovascular disease." (PMID 33071982, 2020). "In conclusion, circulating FABP4 and FABP5 levels are independent predictors each other in patients with type 2 diabetes mellitus." (PMID 33071982, 2020). "Based on rGFR stratum, among the three diabetic subgroups, age, diabetes duration, percentage of hypertension, WC, SBP, RBP4, UACR, and FABP4 all increased with the decrease in rGFR (all P < 0.05)." (PMID 29992142, 2018). "In a cross-sectional study of 270 patients with diabetes and nondialysis chronic kidney disease, 92 patients showed aortic stiffness along with higher levels of FABP4, higher waist circumference and body fat mass." (PMID 38731797, 2024).
diabetes (continued). "Increased CD36 and FABP4 immunostaining were detected in kidney specimens from diabetic patients vs. those without diabetes (respectively) and confirmed via quantitation of immunostaining, respectively)." (PMID 37760019, 2023). "ES-Screen identified previously unreported interactions of the non-steroidal anti-inflammatory drugs (NSAIDs) indomethacin, licofelone, and oxaprozin with human adipocyte fatty acid-binding protein (FABP4) and human aldose reductase (AKR1B1), important targets in metabolic diseases such as diabetes." (PMID 36499162, 2022). "A statistically significant difference was observed in FABP-4 levels among the groups when compared the patients with acromegaly having DM and the controls, with acromegaly having DM and prediabetes, with acromegaly having DM and NGT, respectively (p = 0.014, p = 0.004, p = 0.001)." (PMID 34217172, 2021). "Notably, macrophage depletion in FABP4+/+NOD mice markedly delayed the onset time from 12 weeks to 18 weeks and also significantly reduced the incidence of diabetes from 86.7% to 62.3% at 30 weeks of age." (PMID 33690220, 2021). "To further dissect the contribution of macrophage-expressed FABP4 in autoimmune destruction of β cells and diabetes, we next performed adoptive transfer experiments by transplantation of FABP4–/– and FABP4+/+ bone marrow (BM)into FABP4+/+NOD and FABP4–/–NOD mice, respectively." (PMID 33690220, 2021). "In nonobese diabetic (NOD) mice, increased FABP4 expression in islet macrophages started from the neonatal period, well before the occurrence of overt diabetes." (PMID 33690220, 2021). "Anagliptin decreases serum FABP4 concentration independent of change in hemoglobin A1c or LDL-C in patients with type 2 diabetes mellitus and dyslipidemia who are on statin therapy." (PMID 32539832, 2020). "We investigated concentrations of FABP4 and FABP5 in patients with type 2 diabetes mellitus." (PMID 33071982, 2020). "FABP4 has been reported to have a negative correlation with GDR in type 1 diabetes mellitus, T2DM, and the controls of Asian Americans." (PMID 30857223, 2019). "One gene was identified in the adipose tissue of gerbils with diabetes: Fabp4, also known as adipocyte FABP (A-FABP) or aP2, which is abundantly expressed in adipocytes and may be a mediator of systemic insulin sensitivity and lipid and glucose metabolism." (PMID 29394254, 2018). "The HF subjects with diabetes showed higher FABP4 levels compared to the non-diabetic HF subjects [33.0 μg/L (20.2–76.0) versus 27.8 μg/L (17.2–44.2), respectively, p=0.019], even after adjusting for age, gender, BMI and the eGFR (p=0.002)." (PMID 23642261, 2013). "The difference between FABP4 levels in the HF and non-HF groups remained significant even after the adjusting for age, gender, BMI, and the presence of diabetes and atherogenic dyslipidemia (p<0.001)." (PMID 23642261, 2013). "Given that DCs were reported to be the most important APCs contributing to the pathogenesis of T1D, we tested whether lacking FABP4 expression by DCs was necessary for inducing diabetes in STZ‐treated mice." (PMID 40716098, 2025). "Furthermore, patients with diabetes showed a higher level of FABP4 compared to those without diabetes (19.5 vs. 15.6 ng/mL, p < 0.001, respectively)." (PMID 38731797, 2024). "In another study involving the same cohort FABP4 was shown to correlate with glucose dysregulation, and was predictive for the development of type 2 diabetes in individuals without a previous history of diabetes." (PMID 38698167, 2024). "In the present study, the patients with acromegaly having DM had higher GH levels compared to the patients with acromegaly having prediabetes and NGT, and FABP-4 was found positively correlated to GH." (PMID 34217172, 2021). "The serum FABP4 level can be used as an indicator of microalbuminuria not only in diabetic patients with early stage disease, but also for hyperglycemic individuals before the onset of diabetes." (PMID 30857223, 2019).